TNF (tumor necrosis factor)
Diseases named in the same sentence as TNF in open-access papers (continued):
Sharing a sentence is not in itself a finding about the gene and the disease.
tumor (continued). "In a nude mouse xenograft tumor model, tumor developed from SW1990 and Panc-1 cells stimulated with IL-1β, TNF-α, and Shh was significantly promoted compared to control animals, whereas no stimulating effect was observed on tumor development from BxPC-3 cells." (PMID 34046348, 2021). "Exposure of HT–29 tumor cells and blood samples to 5-FU SF/PEG NPs augmented the tumor necrosis factor-α levels." (PMID 34069731, 2021). "Among these tumor cell lines, only HeLa, HCT116, U2-OS were sensitive to treatment with TNFα/siTPL2." (PMID 34166365, 2021). "Like these pro-inflammatory cytokines (TNF-α, IL-6, and IFN-γ), HA is another principal constituent in the stromal tissues surrounding tumor tissues." (PMID 34770956, 2021). "In vitro analysis highlighted an immunosuppressive cytokine profile in tumour involved lymph nodes consisting of higher levels of IL6, IL10, and TNFα released under stimulation, while IFNγ release was high in cells from tumour free lymph nodes." (PMID 34640541, 2021). "The incidence of tumours was directly correlated with anti-PD1 treatment, alanine aminotransferase (ALT), NAS, number of hepatic CD8+PD1+ T cells, and TNF expression." (PMID 33762733, 2021). "However, acetylated SNAI1 can act as an activator to induce tumor necrosis factor alpha (TNF-α), C-C motif chemokine ligand 2 (CCL2), and C-C motif chemokine ligand 5 (CCL5) gene transcription, which in turn promote carcinoma progression and the recruitment of tumor-associated macrophages (TAMs)." (PMID 34298613, 2021). "CD8+T cells combine with T cell receptors to produce interferon-γ (IFN-γ), tumor necrosis factor (TNF) and granzyme B, which targets tumor cells and results in tumor cell clearance." (PMID 34777372, 2021). "For example, cytotoxic CD8+ T cells can release TNF-α and interferon (IFN)-γ to eliminate tumor cells." (PMID 34831167, 2021). "TAM generates many immunosuppressive factors and chemokines, including IL-6, IL-10, TNF-α, TGF-β, etc., which decrease antigen presentation and impair T cell activity, allowing tumor cells to elude the body’s immunological surveillance." (PMID 34922542, 2021). "This interaction inhibits CD4+/CD8+ tumor-infiltrating T-lymphocytes (CD4+/CD8+ TILs), which results in a decrease in cytokines, such as Interleucin-2 (IL-2), interferon gamma (IFN-γ) and tumor necrosis factor (TNF)." (PMID 34943606, 2021). "Stimulation of NK cells with IL-12 leads to secretion of IFNγ and TNF-α, as well as increased levels of chemokines such as MIP-1α, IL-8 and RANTES, further stimulating the infiltration of CD8+ T cells into the tumor." (PMID 34557197, 2021). "miR-21 activated the PI3K/AKT and NF-κB signaling pathways, leading to initial inflammation; thereafter, miR-21 and TNF-α repressed PDCD4 and its tumor suppression activity." (PMID 34771727, 2021). "After the recognition of tumor antigens, CAR T-cells release massive amounts of perforin/granzymes and cytokines, including TNF-α and IFN-γ, resulting in tumor pyroptosis." (PMID 34794490, 2021). "Ganoderma atrum polysaccharides augmented the host immune response in tumor-bearing mice by activating peritoneal macrophages through TLR4 receptor signaling and promoted secretion of TNF-α via the NF-κB and the p38 MAPK pathways." (PMID 33921554, 2021). "The skewed-to-M1 macrophages usually generate a high level of inducible nitric oxide synthase (iNOS) and tumor necrosis factor-alpha (TNF-α), inclining to kill tumor cells." (PMID 34944555, 2021). "These macrophages secrete proinflammatory factors such as IL-6, IL-12, IL-1β, and TNF-α and highly express MHC class I and MHC class II molecules that recognize tumor-specific antigens." (PMID 34335093, 2021). "In the tumor stage contrasts for STAD and COAD, we see Th2 and NK cells expressing inflammation related genes IL1A, IL1B, IL4, and TNF." (PMID 34512714, 2021).
tumor (continued). "Consistently, we did not observe increased production of the type I cytokines IFN‐γ and TNF among CD4+ Tconv and CD8+ T cells within tumours or spleens." (PMID 33838058, 2021). "Tumor necrosis factor alpha (TNF-α), interferon-gamma (IFN-ƴ), and lipopolysaccharide (LPS) polarize macrophages to the M1 phenotype in vitro, which regulates tumor growth and metastasis and induces Th1 response." (PMID 34207035, 2021). "Pro-tumor N2 neutrophils induce progression of the disease and release of CXCL1, MMP9, VEGF, and TNF-alpha." (PMID 35008550, 2021). "TNFα has been fused with RGD by recombinant DNA technology and has achieved tumor targeting and reduced system damage." (PMID 34959463, 2021). "PD-L1 is highly expressed in a variety of tumor tissues, can be up-regulated by TAM-derived TNF-α, and is positively correlated with macrophage infiltration in tumor stroma." (PMID 34625124, 2021). "In the presence of adenosine, activation of CD8+ T cells effectuates a decrease in the expression of IFN-γ and tumor necrosis factor-α (TNF-α), thereby inhibiting anti-tumor response." (PMID 34778248, 2021). "Conversely, viable tumor cells export HSP70 in exosomes which showed to activate myeloid-derived suppressor cells (MDSCs) and macrophages for the production of IL-6 and TNF-α, respectively." (PMID 33815422, 2021). "The expression of M1 macrophage markers iNOS, IL-1β, TNF-α and CD86 was increased, and the expression of M2 macrophage markers IL-10, Arg-1 and CD206 was reduced in the tumour tissues of tumour-bearing mice." (PMID 34726570, 2021). "Blood transfusions are associated with promoting a proangiogenic environment inducing tumor growth by releasing cytokines IL6, IL10, and TNFα, and regulatory T-cell activation suppressing the anti-tumoral Th1 response." (PMID 34202030, 2021). "Tumor-infiltrating CD4+ T cells and CD8+ T cells from mice given low-dose TSA treatment had an increased frequency of TNF-α and IFN-γ producers compared with vehicle treatment group." (PMID 33564072, 2021). "There is a significant decrease of CD8+/CD4+T cells ratio, NK cells, IL-2, and IFN-γ and a significant increase of T regs, IL-6, IL-1β, TNF-α, IL-10, and PGE2 in CUMS group, indicating the inhibition of immunity in the tumor microenvironment." (PMID 34422050, 2021). "M1 macrophages produce reactive oxygen species (ROS) and proinflammatory cytokines such as Interferon (IFN)-γ, Tumor necrosis factor (TNF)-α, Interleukin (IL)-2, and IL-1β, which play critical roles in killing tumor cells." (PMID 34072260, 2021). "In situ, the combined detection of TNFRSF9, TNF, and IFNG identified most of the tumor-specific reactive TIL repertoire." (PMID 34707600, 2021). "Pro-tumorigenic role: TLR is able to send its pro-tumorigenic signals in tumor cells or in TME by enhancing NF-kB, which, in turn, activates its cascade made up of IL-1β, TNF-α, IL-6." (PMID 34944856, 2021). "M1 macrophages foster the inflammatory response by secreting pro-inflammatory cytokines such as IL-12, tumor necrosis factor-α (TNF-α), CXCL-10, and interferon-γ (IFN-γ) and produce high levels of nitric oxide synthase to exert anti-tumor cell activity." (PMID 34439159, 2021). "5-OP-RU treatment significantly increased the number of IFN-γ and TNF-positive NK cells, confirming that NK-MAIT cell cross talk can occur within a tumor context." (PMID 34362900, 2021). "M1 macrophages secrete IL-6 and IL-12 to mitigate resistance during tumor development; they can also be activated by IFN-γ to secrete TNF to kill cancer cells, while M2 macrophages secrete growth factors that promote neoangiogenesis and tumor proliferation." (PMID 34447376, 2021).
tumor (continued). "Tumor-infiltrating CD8 T+ cells can either produce granzymes or perforin to directly kill tumor cells or produce IFN-γ and tumor necrosis factor (TNF) to mediate cytotoxic antitumor immune responses." (PMID 35242027, 2021). "In terms of CT26 tumor-bearing mice, the combination of NPPA-PTX NPs with aPD-L1 treatment increased the secretions of TNF-α and IFN-γ by 1.57-fold and by 2.03-fold in tumor tissue, by 2.56-fold and by 2.09-fold in serum, respectively." (PMID 33866918, 2021). "This causes the release of inflammatory cytokines such as IFNα and TNF that activate the STAT1 and NF-κB pathways in brain metastatic cells, thereby promoting tumor growth and resistance." (PMID 33466236, 2021). "Under most conditions, cytokine production was similar between spleen and tumor, indicating high potential functionality, with ~75% of cells secreting IFN-gamma and ~nearly 70% producing TNF-α." (PMID 34162858, 2021). "These include IL-6, IL-8 and TNF-α as well as the immune suppressive cytokines IL-10 and TGF-β, which increase HLA-G expression on tumor cells resulting in promotion of evasion from immune cells." (PMID 35111159, 2021). "M1 cells can stimulate antitumoral immune responses by releasing TNF-α and nitric oxide; however, M2 cells can express VEGF, IL-10, TGF-β, and indoleamine 2,3-dioxygenase (IDO), leading to tumor development." (PMID 34947886, 2021). "TNF-α is also related with the acute phase response (APR), activated by trauma, infection, stress, neoplasia, and inflammation." (PMID 34679061, 2021). "Tumours from Osm−/− animals exhibited markedly reduced levels of several cytokines, including IL6, CXCL1, GM-CSF and TNFα, highlighting a profound change in the tumour environment." (PMID 34921158, 2021). "On the other hand, more recent experiments in a TPA/DMBA two-step skin carcinogenesis model suggested that the difference in tumor load between TNF-deficient and co-housed littermate control mice may not be as dramatic as previously reported and is microbiota-dependent." (PMID 33917839, 2021). "It has also been reported that as a tumor promoter, MMP14 acts by inhibiting cell adhesion molecules, and tumor necrosis factor-α (TNF-α) is one of its acting factors." (PMID 34604053, 2021). "Cytokines, such as type-I IFN and tumor necrosis factor-α (TNF-α), are secreted by infected tumor cells, TAAs and viral PAMPs are exposed to the host immune system followed by oncolysis." (PMID 33985527, 2021). "Of these, TNF-α, IFN-β, TSLP, and sVCAM-1, identified to be elevated in haematological cancers, are also known tumour-promoting factors." (PMID 34830872, 2021). "For example, inflammatory factors IL-6, IL-8 and TNF-α can induce the expression of vascular endothelial growth factor (VEGF) and activate NF- κB, EGFR, TLR and other signal pathways, thus stimulating tumor cell proliferation." (PMID 34956913, 2021). "The TNF-α-NF-κB pathway was also enriched in macrophages from SA-ESCC, implying that SA-ESCC macrophages in the TME enhance tumor development and dissemination, consistent with previous studies." (PMID 34697289, 2021). "The ascites from the obese cKO mice showed increased vacuole clumps but decreased the floating tumor burden, tumor-attached macrophages, triglyceride, free fatty acid, CCL2, and TNF levels compared to obese WT mice." (PMID 34638514, 2021). "Estrone more effectively raised levels of mRNAs for CCL2 and IL-6 in MCF7 cells pretreated with TNFα than 17β-estradiol, which was validated in MCF7 tumor-bearing mice treated with estrone." (PMID 34359625, 2021). "In this study, we found that compared with the tumor group alone, the NK-exosome-treated tumor group exhibited a significant decrease in the expression of CD133, Bmi-1, MMP-3, IL-1β, IL-6, and TNF-α." (PMID 34527741, 2021). "TNF, IFNγ and CXCL10 levels were significantly increased in plasma of mice with RM-1 tumors compared to tumor naïve mice." (PMID 33786638, 2021).
tumor (continued). "GPx4 inhibits tumor angiogenesis and malignancy through blocking eicosanoid synthesis, including COX-2, prevented TNF-mediated activation of cytokine-driven NF-κB and prostaglandin PGE2 production and abrogated PGE2-dependent COX-2 expression." (PMID 34394838, 2021). "BV decreases the activation of nuclear factor κB (NF-κB) and MAP kinase and leads to a reduced expression of tumor necrosis factor-α (TNF-α), interleukin-1β (IL-1β) inducible nitric oxide (iNO), and cyclooxygenase-2 (COX-2), thus diminishing the skin damage." (PMID 34822594, 2021). "Activated NK cells are cytotoxic to tumor cells and produce immunomodulatory cytokines, such as interferon (IFN)-γ and tumor necrosis factor (TNF)-α." (PMID 33920906, 2021). "Similar patterns were observed in TILs from B16.F10 tumors, where the bystander cells contained 1.5-fold more IFN-γ+ TNFα+, and 3.4-fold more IFN-γ+ IL-2+ cells compared to tumor-Ag sp." (PMID 34867942, 2021). "The enhanced cytolytic activity and the increased serum IFN-γ and TNF-α concentration in vitro, as well as the increased serum IFN-γ concentration in vivo indicated that LSD1 shRNA co-expression improved the anti-tumor function of anti-CD19 CAR-T cells." (PMID 35046962, 2021). "The AuNP conjugates preferentially accumulated in the tumor sites after systemic administration through the EPR effect and vascular targeting effects of the TNF-α." (PMID 34866165, 2021). "In the cytotoxicity against tumor cells, the release of ECP, EDN, TNF, and granzyme A have been involved, however eosinophils can induce apoptosis of CRC cells (Colo-205) also through production of reactive oxygen species (ROS) and EPO release." (PMID 33917620, 2021). "Before T-cell transfusion, the ability of NRT cells to specifically identify and mediate efficacy functions in response to Lewis tumour cells in vitro was evaluated through IFN-γ and TNF-α production and ELISpot assay." (PMID 34291357, 2021). "The pro-inflammatory cytokines (TNF-α, IL-12, IFN-γ and IL-2) increased in the spleen of tumour-bearing mice that had been treated with VES, whereas the anti-inflammatory cytokine IL-10 decreased transcriptionally." (PMID 34093795, 2021). "As an indicator for indirect anti-tumor activity of NK cells, we measured the amount of GM-CSF, IFN-γ, and TNF-α, which were released by NK cells into the cell-culture medium." (PMID 34925361, 2021). "Transmigration into the extravascular space is thought to be mediated by TNF-α and ICAM interaction between tumor and endothelial cells." (PMID 33800796, 2021). "Administration of even a low dose of TNF-α has shown increased expression of immunosuppressive molecules PDL-1 and TIM-3 on TIL and activate cell death pathways in tumor-infiltrating CD8+ CTL." (PMID 34012451, 2021). "Among the increased systemic proinflammatory cytokines, TNF-α and IFN-γ were frequently reported to have anti-tumor activity." (PMID 33953170, 2021). "Microglia can produce MCP-1 through TNFα/TNFR1 signaling triggered by peripheral inflammation, which, in turn, attracts the migration of microglia/macrophage into the tumor." (PMID 34575110, 2021). "At the same time, TApDCs not only exhibit less production of IFN-α, mainly mediated through tumor-derived TNF-α and TGF-β, but also induce tumor infiltration of ICOS+ Foxp3+ Tregs and drive immunosuppression via ICOS/ICOSL stimulation." (PMID 34737750, 2021). "The alternative polarization, induced by Th2-derived cytokines (e.g., IL-4, IL-10, IL-13) that hamper the production of pro-inflammatory cytokines such as TNF-α and IFN-γ, gives rise to the pro-tumor M2 macrophage phenotype." (PMID 33816242, 2021). "Upon activation, tumor-specific CD8+ T cells secrete IFN-γ, tumor necrosis factor (TNF)-α, and cytotoxic mediators." (PMID 34359708, 2021). "Neoplastic cells producing chemokines (e.g. CXCL1), cytokines (TNF-α and IFN-γ) and adhesion proteins can also recruit neutrophilic granulocytes to the tumor microenvironment." (PMID 33146401, 2021).
tumor (continued). "A previous study showed that TNFα activated MAPK/ERK signals, leading to an increase in the tumor invasiveness in breast cancer." (PMID 34764346, 2021). "We found that in PRMT5 knockdown tumor microenvironment, the expression of IFN-γ and TNF-α in CD4+ T and CD8+ T cells were increased, and the expression of granzyme B in CD8+ T cells was also upregulated." (PMID 34522232, 2021). "Some of our previous findings have shown impairment of the placenta due to the presence of cancer or some tumour factors, such as proinflammatory cytokines interleukin-6 (IL-6), interferon-gamma (IFN-γ), and tumour-necrosis factor (TNFα)." (PMID 33916290, 2021). "In addition, the expression of key genes in the TNF-α/NF-κB signaling, including NFKB1 (p50), RelA (p65), TNFRSF1A (TNFR1), TNFR1-associated death domain protein (TRADD), and TNF receptor-associated factor 2 (TRAF2), was examined in the cell lines and tumor tissues of EBV-associated cancers." (PMID 35008199, 2021). "It possessed a worthy and promising therapeutic effect due to the improvement in the tumor biomarkers as AFP, TNF-α, Caspase- 3, VEGF, TGF-β1, CEA, and reduction of the lipid peroxidation." (PMID 34319038, 2021). "We chose serum TNF-α, IFN-β, and IL-6 as the investigated cytokines, which were secreted by the activated immune cells and essential factors to eliminate tumor cells." (PMID 34541546, 2021). "In breast cancer, an anti-CXCL13 antibody suppressed tumor growth by inhibiting the TGF-β1, IL-1, TNF, cyclin D1, and CXCR5/Erk pathways and repressed tumor metastasis by inhibiting RANKL production." (PMID 34947813, 2021). "Tumor necrosis factor alpha (TNF-α) is a pleiotropic cytokine that mainly mediates anti-tumor effects, but this cytokine can also promote tumor progression." (PMID 34379689, 2021). "The initial step of premetastatic niche formation in specific organ sites is mediated by tumor‐derived soluble factors such as TNF‐α, TGF‐β, CXCL12, placental growth factor and VEGF‐A49 as well as by tumor‐derived exosomes." (PMID 32761606, 2021). "TAMs can directly promote the proliferation of tumor cells by secreting growth factors and inflammatory mediators such as CCL2, IL-1α, IL-6, and TNF-α (step 3)." (PMID 33968034, 2021). "Especially, the combination of NPPA-PTX NPs with aPD-L1 treatment increased the secretions of TNF-α and IFN-γ by 1.87-fold and by 2.34-fold in tumor tissue, by 3.12-fold and by 2.10-fold in serum on 4T1 tumor-bearing mice, respectively." (PMID 33866918, 2021). "In tumors, it is thought that the activity of TNF-α may be related to the tumor microenvironment at the local level of the adipose tissue, where it acts as a signaling molecule, either at the paracrine or autocrine level, regulating the different processes of tumor development and progression." (PMID 34074045, 2021). "In the ovarian cancer mouse model, I-BET151 treatment inhibits the Stat3 signaling pathway, induces more CD3+ and CD8+ cells in the tumor, increases TNF-α and IFN-β mRNA levels in the tumor and mouse spleen, and induces an anti-tumor immune response." (PMID 34540687, 2021). "Consistently, increased levels of circulating pro-inflammatory cytokines, such as TNF-α, IL-6 and MCP-1, have been reported in cachectic tumor-bearing mice, as well as in cancer patients." (PMID 33671024, 2021). "Expression of certain ‘pro-tumor’ cytokines such as tumor necrosis factor-α (TNF-α), interlukin-6 (IL-6), and IL-8 have been found to promote tumor growth and metastasis." (PMID 34771675, 2021). "Tumor necrosis factor-α (TNF-α), a multifunctional cytotoxic molecule that cannot only induce tumor cell apoptosis and necrosis but can also stimulate release of other cytokines and recruit immune cells." (PMID 34367111, 2021). "On the other side, COX-2 is mainly induced in response to various endogenous and exogenous stimulus such as cytokines (tumor necrosis factor α (TNF-α), interleukins (IL-1 and IL-6), tumor promoters (v-src, v-Ha-ras, and Wnt)) and stress." (PMID 34961132, 2021).